BRCA1 (BRCA1 DNA repair associated)
Diseases named in the same sentence as BRCA1 in open-access papers (continued):
Sharing a sentence is not in itself a finding about the gene and the disease.
cancer (continued). "It is not clear why this immunological effect on therapeutic outcome is particularly impactful in nonBRCA cancers since this immune signature appears also in BRCA1 deficient cancers." (PMID 35857626, 2022). "This study reported no pathogenic variants in BRCA1/2 genes and other cancer predisposing genes which disagrees with our findings." (PMID 36672847, 2022). "In fact, DCIS was reportedly rare in BRCA1 carriers, or even not considered as part of the cancer spectrum risk conferred by BRCA1 PSV." (PMID 36349178, 2022). "Our GeneseeqPrime HRD panel is an integrated NGS panel that could evaluate HRD score and target 425 cancer-related genes including but not limited to BRCA1/2 and other genes in the HRR pathway." (PMID 35578198, 2022). "By eliminating precancerous cells or preclinical cancers, double-strand DNA breaks-inducing chemotherapeutics may reduce the occurrence of CBC in BRCA1/2 mutation carriers." (PMID 34929424, 2022). "If similar responses were found in cancer patients, then individuals with the mtDNA J haplogroup might have higher levels of BRCA1 that might provide protection since it maintains genomic stability by repairing DNA breaks and yields tumor suppression." (PMID 35743133, 2022). "Recently, the term BRCAness was developed to refer to cancers that have the phenotype of BRCA1/2 mutations due to non-BRCA DDR alterations, epigenetic modulation and post translational modification." (PMID 36358724, 2022). "The study results suggest that the range of cancer types associated with pathogenic variants in BRCA1 and BRCA2 is broader than that determined from previous analyses, potentially indicating the broader clinical relevance of BRCA1/2 genetic testing." (PMID 35420638, 2022). "Unlike normal cells, BRCA1/2-deficient cancer cells critically depend on PARP1 for backup DNA repair leading to selective killing of these cancer cells by targeting PARP1 and recent regulatory approval of several PARP1 inhibitors (PARPis) for BRCA1/2-linked OC." (PMID 36183837, 2022). "Three patients in the SG arm and none in the TPC arm had known germline breast cancer susceptibility gene 1 or 2 (BRCA1/2) mutations." (PMID 35680967, 2022). "There is an association between BRCA1 gene carrying and missed cancers, more often overlooked in patients not carrying the BRCA1 gene (79%) compared with carriers (59%) OR 2.621, 95% CI [1.02, 6.74] p < 0.05." (PMID 35202192, 2022). "The patient and his father carry the germline mutation of BRCA1 (c.4166G>A, p.S1389N), with no cancer history of other family members." (PMID 35734583, 2022). "Moreover changes in the BRCA1 and BRCA2 genes show an increased risk for the formation of neoplasms of other organs, including cancers of the: prostate, fallopian tube, pancreatic, bladder or melanoma." (PMID 35395863, 2022). "Cancers lacking BRCA1 are susceptible to cisplatin because of the accumulation of DSBs due to the inability of DNA repair by HR." (PMID 35204785, 2022). "The available information on BRCA1/2-related cancers is directed mainly at women, reflecting a gendered approach that may lead men to underestimate their risk of carrying BRCA mutations." (PMID 35303741, 2022). "Besides working effectively in BRCA1/2-mutated cancers, PARPi-mediated synthetic lethality is capable of sensitizing c-NHEJ-deficient cancer cells." (PMID 36497275, 2022). "Based on a methylation threshold of 70%, low-methylation cancers showed BRCA1 expression akin to those found in nonBRCA1 cancers, wehereas cancers with high-methylation showed a reduction in BRCA1 expression to less than 10% of what observed in nonBRCA1 cancers, (P = 3.1E-8, fig." (PMID 35857626, 2022).
cancer (continued). "We searched for both germline and somatic pathogenic variants in BRCA1/2 and BRCAness genes in each of the 33 cancer types and identified a total of 808 germline and 4017 somatic pathogenic mutations in BRCA1, BRCA2 and 37 of the 38 BRCAness genes distributed in 33 cancer types." (PMID 36497135, 2022). "In the present study, patients with family history of cancers were also more likely to harbor BRCA1/2 mutations (7.7%/13.3%) than patients without family history (1.6%/5.3%)." (PMID 35494038, 2022). "When the tumour harbours a BRCA1/2 mutation (germline or somatic), the resulting HRD prevents the repair of double-stranded DNA breaks, which accumulate to the point of genomic catastrophe and trigger cancer cell death." (PMID 35735457, 2022). "BRCA1 mutant cancer cells rely on alternative DNA-repair pathways in the absence of HR." (PMID 36346676, 2022). "The discovery of BRCA1 and BRCA2 gene pathogenic variants has made it possible to identify high oncologic risk populations and improve their life expectancy with individualized screenings, early cancer diagnosis, novel therapies and prophylactic procedures." (PMID 36497251, 2022). "In addition to BRCA1/2 aberrations, other genes involved in HR repair such as RAD51C, RAD51D, PALB2 and BRIP1, are known to be mutated in many cancer types." (PMID 36284291, 2022). "Indeed, the successful development of novel drugs such as PARP inhibitors (PARPi), which target BRCA1 and BRCA2-deficient cancers, support this proof of concept." (PMID 35610507, 2022). "However, beyond BRCA1/2 carriers only showed significant differences in cancer sites when compared with non‐carriers." (PMID 35608067, 2022). "Synthetic lethal interactions (SLIs), genetic interactions in which the simultaneous inactivation of two genes leads to a lethal phenotype, are promising targets for therapeutic intervention in cancer, as exemplified by the recent success of PARP inhibitors in treating BRCA1/2-deficient tumors." (PMID 36761837, 2022). "Altogether, various factors and life stages play a role in cancer concerns that may affect BRCA1/2-PV carriers." (PMID 34997316, 2022). "Two machine-learning algorithms that predict HRD status, CHORD, and HRDetect, utilize various HRD-associated features extracted from whole-genome sequencing (WGS) data and show high sensitivity in detecting patients with BRCA1/2 bi-allelic inactivation in all cancer types." (PMID 35783256, 2022). "Patients with family history of cancers were more likely to be BRCA1 carriers." (PMID 35494038, 2022). "In addition to the recommendation for genetic counseling, three variants likely associated with an autosomal dominant cancer disposition supported a treatment recommendation, twice for PARP inhibition (BRCA1, CHEK2) and once for CDK4/6 inhibition (CDKN2A)." (PMID 35918329, 2022). "In the process, the PARP inhibitors block PARP function of repairing single-strand breaks and cause the formation of double-strand break upon replication, which cannot be repaired by homologous recombination due to the defected BRCA1/2 function leading to the death of cancer cells." (PMID 36497135, 2022). "BRCA1/2 mutation carriers without cancer should have early and regular cancer screening, and prophylactic measures." (PMID 35205313, 2022). "This applies especially to young BRCA1/2-PV carriers since cancer risks are still low at young age, cancer worry decreases with an increasing time since BRCA diagnosis irrespective of surgery, and, in general, the younger age at sterilizing surgery the higher the risk of regret of this surgery." (PMID 34997316, 2022). "Results have shown a significant association of mutations in BRCA1/2 and RAD51C with cancer risk." (PMID 35313928, 2022). "We therefore assessed causal attributions made by women with a pathogenic germline variant in BRCA1/2 (gBRCA1/2-PV), both with and without a cancer diagnosis." (PMID 36011311, 2022).
cancer (continued). "Although BRCA1 and BRCA2 are ubiquitously expressed in cells of the human body, pathogenic germline mutations in these genes confer significantly elevated risk of developing various cancers, notably, cancers of the breast and ovary." (PMID 35668475, 2022). "This may be attributed to a novel role in the motility and migration of cancer cells that were proposed for cytoplasmic and membranous localised BRCA1 and BRCA2 proteins." (PMID 34045664, 2022). "Even though a correlation between the number of relatives with cancer and family size cannot be disregarded in our cohort, the performance of familial history in risk prediction for PV/LPV in BRCA1/2 genes might be of importance in the Brazilian population." (PMID 36329109, 2022). "Finally, the increasing use of BRCA1/2 testing in somatic tissues for tailoring cancer treatment, in addition to classical germline testing for inherited predisposition diagnosis is switching the classical prevention scenario to mainstream oncology practice." (PMID 35267543, 2022). "Mutations in BRCA1 and BRCA2, which impair their normal function, have been associated with an elevated risk of breast and ovarian cancer, as well as an increased risk of pancreatic, prostate, stomach, and many other cancers." (PMID 35626055, 2022). "We observed high cancer worry prior to risk-reducing gynaecological surgery in 57% of all BRCA1/2-PV carriers, without differences between women who chose RRS or RRSO." (PMID 34997316, 2022). "Consistent with this role, faults in the DDR (for example those caused by deleterious mutations in DNA repair associated tumour suppressor genes such as BRCA1 and BRCA2) provide the mutagenic fuel that drives oncogenesis and are well described as drivers and hallmarks of cancer." (PMID 35567571, 2022). "How and why distinct genetic alterations, such as BRCA1 mutation, promote tumorigenesis in certain tissues, but not others, remain an important issue in cancer research." (PMID 35327946, 2022). "BRCA2-PV carriers had a 0.8 points higher cancer worry than BRCA1-PV carriers." (PMID 34997316, 2022). "Co-occurrence of mutations that increase immunogenicity (e.g., BRCA1) with those enabling immune escape (e.g., CASP8) suggests a model of cancer progression where immune-mediated selection is a later event, in the setting of an otherwise immunogenic population." (PMID 35437329, 2022). "Although germline BRCA1/2 mutation status is unknown in this cohort, the design of the signature means that any BRCA-associated cancers will likely be identified as DDIR positive due to their intrinsic DNA-repair deficiency." (PMID 34728791, 2022). "But it may be associated with PARP and BRCA1, because PARP inhibitors induce anti-cancer effect in BRCA1-mutant cancer types, and LCS-1 induced the degradation of both PARP and BRCA1 simultaneously." (PMID 35978820, 2022). "Although triple negative cancers are diagnosed more frequently in BRCA1/2 gene mutation carriers than in the population of genetically non-burdened patients of the same age, the vast majority of cancers show expression of hormone receptors." (PMID 35887761, 2022). "Compared to women affected by sporadic BC or OC, BRCA1/2 mutation carriers without a history of cancer, in the following referred to as ‘previvors’, develop BC or OC about 20 years earlier in their life." (PMID 35172875, 2022).
cancer (continued). "In particular, decreased PLP levels may increase cancer susceptibility by stimulating LOH when a muted copy of a tumor suppressor gene, such as BRCA1/2 or Rb1 is inherited in the germline." (PMID 35682766, 2022). "The use of PARPIs in non-BRCA mutation carrier patients can be expanded to sporadic cancers that display “BRCAness” (cancers that have defective HR without germline BRCA1 and 2 mutations)." (PMID 35785170, 2022). "Several studies demonstrated that unlike normal cells, RAD52 is required for the survival of cancer cells with loss-of-function mutation in genes such as BRCA1, BRCA2, PALB2, and RAD51 paralogs." (PMID 35463312, 2022). "While an association between BRCA1 methylation in normal tissue and TNBC and HGSOC was established previously, these studies were performed on normal tissue obtained after the patients received their cancer diagnoses." (PMID 36074460, 2022). "However, there is considerably less research on the psychological determinants of men engaging in BRCA1/2-related cancer prevention compared to women." (PMID 35303741, 2022). "Such agents are also of specific interest in cancers that harbor defects in DDR pathway components, where they may create a synthetic lethal-like interaction, as in the case of poly (ADP-ribose) polymerase (PARP) inhibitors in BRCA1 or BRCA2 mutant cancers." (PMID 36309653, 2022). "BRCA1 and BRCA2 are the two most well-known cancer predisposition genes." (PMID 35625955, 2022). "Current research is investigating the potential that PARP inhibitors may work in cancers with wild-type BRCA1/2 but high levels of BRCAness." (PMID 35158750, 2022). "Most of the therapeutic strategies using PARP inhibitors rely on their blockade of DDR and the creation of synthetic lethality in combination with genetic defects in homologous recombination-mediated repair, which are the basis for the treatment of patients with BRCA1- and BRCA2-associated cancers." (PMID 35545049, 2022). "Here, again, the ratio of nonBRCA cancers to BRCA1 deficient cancers will likely determine how effective immune scores are in predicting chemotherapeutic response." (PMID 35857626, 2022). "However, the synthetic lethal pair of BRCA1, the poly (ADP-ribose) polymerase 1 (PARP1) gene, has been shown as conserved in mostly BRAC1 mutated (BRCA1m) cancer cells and seems to be a promising pathway in sensitizing these cells to chemotherapy." (PMID 35879772, 2022). "TNBC is the most aggressive type of cancer and is tough to cure not only due to the lack of molecular target receptors but also the presence of BRCA1 mutations causing chemotherapeutic drug resistance elevating risks of disease recurrence." (PMID 35879772, 2022). "Thus, our aim was to investigate different geographic locations throughout Turkey to determine the most common cancer-related genetic variations in the BRCA1/2 genes based on regions." (PMID 35753294, 2022). "Of note, in different human cancer cells, BRCA1 globally represses ERα activity." (PMID 36230510, 2022). "The commonly known carcinogens of smoking and alcohol intake do increase cancer in general but especially in combination with an underlying CPS such as BRCA1/2 PV carriers and were not abandoned in our high-risk cohort." (PMID 36290891, 2022). "Due to the challenges of detecting reversion mutation and the limited usage of PARP inhibitors in clinical trials, data gathered from massive-scale research to assess the prevalence of BRCA1/2 gene reactivation in cancer patients having PARP inhibitor-resistant tumors are missing even now." (PMID 35873570, 2022). "BRCA1 depletion promotes TGFβ-mediated EMT activation in cancer cells." (PMID 35236825, 2022). "A previous study in women from BRCA1/2 mutation-negative families reported that women who had a higher perceived lifetime risk of cancer and higher worry about cancer were more likely to show an interest in genetic testing." (PMID 35606835, 2022).
cancer (continued). "On the other hand, the penetrance of BRCA1/2 mutations is not complete, and there is substantial variability in age of cancer onset among carriers." (PMID 35625955, 2022). "The transition of BRCA1-KO fibroblasts to carcinoma-like cells (i.e., mesenchymal-to-epithelial transition) could be induced by sEV-gDNA (along with sEV-associated regulators) without preceding epithelial-to-mesenchymal transition." (PMID 36003770, 2022). "Mutations in BRCA1, BRCA2, and PALB2 are strongly associated with cancer predisposition." (PMID 34830134, 2021). "Another pathogenic variant in a TNBC case, a frameshift deletion mutation p.Ser956ValfsTer13, rs80357819, in BRCA1 is detected in a case aged 32 with no family history of cancer." (PMID 33773534, 2021). "Since the cyclin E1 degradation machinery was deregulated in BRCA1 mutant cancers across our cohort, we investigated whether cyclin E1 turnover is dysregulated in cell lines with mutant BRCA1 or BRCA1 loss." (PMID 34465787, 2021). "For example, using a Polθ inhibitor in combination with or after a PARP inhibitor in patients with BRCA1 mutant cancers might prevent the emergence of otherwise drug resistant 53BP1/Shieldin defective tumour cell clones." (PMID 34140467, 2021). "The effect is greatest for BRCA2 mutations, probably because women with BRCA1 mutation more often develop estrogen and progesterone negative cancers." (PMID 33996049, 2021). "Targeting the BRCA1/BARD1 complex may provide a promising strategy for those tumors in cancer therapy." (PMID 34789768, 2021). "Deletion in both BRCA1 and Beclin1 or only BRCA1 was found, but no proof of Beclin1 mutation or loss detected in any cancer which questions its tumor silencing activity in human cancer." (PMID 33628386, 2021). "We also investigated the performance of imaging modalities in patients with mutations in non-BRCA1/2 cancer predisposition genes which affected no less than 5 patients." (PMID 34336698, 2021). "Identifying carriers of BRCA1 and BRCA2 pathogenic variants for cancer prevention (prophylactic surgery) and management of OC using new therapies (e.g. poly (ADP-ribose) polymerase inhibitors (PARPi)) is being offered in medical genetic and gynecologic oncology settings." (PMID 34861889, 2021). "Moreover, in addition to RAGE, other repair factors such as BRCA1, RAD51 and Mdm2 are known to express their multiple splice variants in SCLC and other cancers." (PMID 34200336, 2021). "Several cancer-related genes, including BRCA1 and MLL (Myeloid/Lymphoid or Mixed-Lineage Leukemia; KMT2A, Lysine Methyltransferase 2A) contain many copies of the Alu element, which is the most abundant transposon in the human genome, accounting for about 10% its sequences." (PMID 33671579, 2021). "Like TWIST, FOXC1/2 expression is upregulated in BRCA1-mutant cancer cells." (PMID 35008272, 2021). "Loss of BRCA1 function in cancer cells can lead to absence of intact homologous recombinant DNA repair, and result in cells being more sensitive to agents that cause DSBs." (PMID 34820332, 2021). "The dysregulated circAKT3 acts as a miR-198 sponge to activate the PI3K/AKT signaling pathway and upregulate the DNA damage repair molecule breast cancer 1 (BRCA1), which inhibits cancer cell apoptosis and also leads to resistance in DNA-damaging CDDP-based chemotherapy." (PMID 33710802, 2021). "We presumed that high ATF1 expression confers resistance to PARP inhibitors in cancer cells with HRD because of the alteration of non-BRCA1 HR factors, such as BRCA2, in which sufficient ATF1 and intact BRCA1 could stimulate ATF1-mediated transactivation." (PMID 36860287, 2021). "Also, the reduced BRCA1 and RAD51 expressions in VHL-mutated cancers highlight the involvement of HIFs in HRR factors down-regulation and radiation-induced DSBs persistence." (PMID 34539584, 2021).